CDK2 (cyclin dependent kinase 2)
Diseases named in the same sentence as CDK2 in open-access papers (continued):
Sharing a sentence is not in itself a finding about the gene and the disease.
cancer (continued). "In our study, in addition to confirming that CDK2 is a marker of poor prognosis, we have found that this gene harbors genomic amplifications and splice mutation and that its expression: (i) is upregulated in OSCC patients; (ii) correlates with cancer grade; and (iii) is associated to HPV infection." (PMID 36768994, 2023). "Additionally, previous investigations in mouse cancer cell lines unveiled that circFoxo3, p21, and CDK2 form ternary complexes, enhancing the interaction between the two proteins while simultaneously preventing the formation of a cyclin E/CDK2 complex." (PMID 38132133, 2023). "Additionally, it is assumed that propolis extracts exhibit cytotoxicity by targeting cell cycle regulators such as cyclin D, cyclin-dependent kinases Cdk-2/4/6, and cyclin-dependent kinase inhibitors, thereby arresting the progression of the cancer cell cycle at the G2/M and G0/G1 phases." (PMID 36364287, 2022). "Furthermore, transfection of antisense oligonucleotide of miR-25 has downregulated the overexpressed miR-25 in SCLC cell line, resulting in decreased amount of cancer cell proliferation, invasion and resistance to cisplatin by suppressing the expression of cyclinE2 and CDK2." (PMID 36303933, 2022). "This inhibitor of cyclin E (cyclin-dependent kinase 2, Cdk2) activity stops the cell cycle at the G1-S stage, while non-proliferating cells differentiate or undergo apoptosis, which can be interpreted as effects that limit the occurrence and progression of cancer." (PMID 36233008, 2022). "However, we investigated whether we would be able to target other concurrent genetic mutations or develop novel strategies to treat CCNE1 amplified cancer cells via synthetic lethal interaction other therapeutics, such as Wee1 kinase or CDK2 kinase inhibition." (PMID 35610322, 2022). "Therefore, we supposed si-NR1H4 suppressed malignant phenotype of ccRCC cells due to the downregulation of CCNE2/CDK2 which could help cancer cells switch from G0/G1 to S phase." (PMID 36123627, 2022). "Therefore, CDK2 is a critical molecule that modulates the SKP2/P27 axis in human cancers." (PMID 35313079, 2022). "Besides, the small molecule roscovitine (seliciclib) inhibited CDKs 2 and 5 with suspending the proliferation of rapidly growing mammalian cancer cell lines with an IC50 value of 16 μM for CDK2 and induced growth arrest in G1-phase and accumulation in G2-phase." (PMID 33466812, 2021). "In addition, our KEGG pathways and gene ontologies studies showed that the CDK2/4/6 and STAT3 clustering PPI network were associated with pathways and processes involved in the cell cycle, DNA replication, cell communications, immune response, and cancers." (PMID 33668805, 2021). "Therefore, we explored associations of CDK2/4/6/STAT3 expressions with infiltrating immune cells (CD4+ T cells, B cells, CD8+ T cells, neutrophils, dendritic cells, and macrophages) in multiple cancers." (PMID 33668805, 2021). "Furthermore, significantly elevated expressions of CDK2, CDK4, and CDK6 are well documented in HCC and many other cancers, and they are the causal factors for the development and progression of cancer." (PMID 33579185, 2021). "However, as a CDK2/4/6 triple inhibitor, vanoxerine dihydrochloride may have broader activity and will be effective to a larger number of cancers than CDK2 or CDK4/6 inhibitors." (PMID 33579185, 2021). "However, so far, no CDK inhibitor has been approved for the treatment of HCC or other cancers, suggesting the need to find more effective drugs, and a CDK2/4/6 triple inhibitor may be a potential candidate." (PMID 33579185, 2021). "The buffered cell cycle progression induced by PAX-FOXO1 proteins _a slow cycling state_ could underlie the refractory response of FP-RMS cells to drugs such as CDK2 inhibitors and contribute to the elevated resurgence of tumours post-treatment, as shown for other cancers." (PMID 33175861, 2020).
cancer (continued). "Importantly, we observed one cancer cell line in which elevated cyclin E1 caused by knockdown of FBXW7 did not appear to activate CDK2 (as measured by pNPM)." (PMID 32076484, 2020). "Some cancers may transition through a low-CDK2 state at early, possibly benign periods of growth." (PMID 31223310, 2019). "Potent CDK2 inhibitors might target certain cancers in which CCNE1 is amplified." (PMID 30472117, 2019). "Overall, our findings provide enough evidence that the compound 101874157 might be a promising scaffold for CDK2 inhibition and can be further exploited as a lead molecule with required modifications to design potent and selective inhibitors of CDK2 to control cancer progression." (PMID 31847444, 2019). "However, the present study is the first to demonstrate that buforin IIb inhibits cell proliferation by regulating the cell cycle via mediating the expression of CDK2 and cyclin A. This information extends the scope of the understanding of buforin IIb's effects on cancer progression." (PMID 31231581, 2019). "Thus, suppression of CDK2 by miR-3140 may contribute to the inhibition of tumor growth in some cancers." (PMID 29540837, 2018). "To test whether CDK2 KO mice were protected against cisplatin ototoxicity in vivo, we adopted a protocol in which multiple low-dose cisplatin treatments were administered to mimic the cisplatin regimens used to treat patients with cancer." (PMID 29514916, 2018). "Furthermore, CDK1 and CDK2 are both drug targets of the investigational drug Alvocidib which is a synthetic flavonoid based on an extract from an Indian plant for the potential treatment of cancer." (PMID 29855504, 2018). "Furthermore, Curcumin induced G1 cell cycle arrest, which is regulated by CDK2 in cancer cells." (PMID 29890691, 2018). "In addition, expression levels of cell cycle (CDK2, CDC2, CCND2) and inflammation markers linked to cancer (NOS2, TGFβ1, CHI3L1 and TFPI) were significantly increased in Caco-2WT/miR-373 compared with Caco-2WT/miR-c, but decreased in Caco-2D299G/α-miR-373 compared with Caco-2D299G/α-miR-c." (PMID 27271572, 2016). "For example, CDK2 has not been found mutated in human cancer." (PMID 25914884, 2015). "Hence, CDK2 inhibitors are potentially effective anti-cancer agents." (PMID 26147897, 2015). "Thus, further investigations of this new phosphorylation site on HSF1 and its predicted cell-cycle-dependent upstream kinase, CDK2, may lead to new insights on the role of this heat-shock protein in cancer." (PMID 26388441, 2015). "Finally, CDK2, LST1, NKD2 and RASL11B have also been implicated in a variety of cancer types." (PMID 22087225, 2011). "Thus, OGF exerts its effects in these cancer cells by inducing Cdk2/p21 complexes." (PMID 18190706, 2008). "In addition to these peptidomimetics of CDKN1A, SDCs, called 'dimerizers', that induce or stabilize CDK2/cyclin A/CDKN1A protein complex could potentially lead to treatments for cancer." (PMID 17705877, 2007). "Could the combined targeting of Cdk2 and Cdk4 be a valuable approach for cancer therapy?" (PMID 16759374, 2006). "sylvestris flowers and predicted to target the human CDK2 transcript-resulted in gene silencing, thereby suggesting its central role in mediating the cross-kingdom effects of MFE on the investigated cancer models." (PMID 41683317, 2026). "CDK2 is the kinase that phosphorylates Mxc/NPAT for histone gene activation, linking conserved HLB regulation described here to a deeper understanding of cancer." (PMID 41491041, 2026). "Owing to its potential role in regulating cancer cell cycle progression and driving therapeutic resistance to CDK4/6 inhibitors, CDK2 has been considered as an important target for therapeutic intervention." (PMID 39924553, 2025). "Molecular docking revealed strong binding affinities between these compounds and cancer-related targets (AKT1, CDK2, ERK1, TNFα), with simplicildone D and mollicellin G demonstrating particularly high interactions." (PMID 40942174, 2025).
cancer (continued). "Specifically, nine depsidone compounds were subjected to in silico docking against key cancer-related protein targets, including AKT1, CDK2, ERK1, and TNFα." (PMID 40942174, 2025). "Cancer cells rely heavily on CDKs like CDK1, CDK2, and CDK9 for uncontrolled proliferation, whereas normal cells maintain cell cycle control with minimal CDK activity, making them less susceptible to Dinaciclib-induced cytotoxicity." (PMID 40076816, 2025). "This study investigates the anti-cancer mechanisms of curcumin on CRC progression, focusing on PTBP1 and CDK2 as critical regulators." (PMID 40469179, 2025). "By simultaneously targeting CDK2, EGFR, and Tubulin, this multi-targeted therapy addresses multiple pathways involved in cancer cell survival, proliferation, and metastasis." (PMID 40526618, 2025). "Targeting cyclin-dependent kinase 2 (CDK2), a critical cell cycle regulator, is a promising approach for cancer treatment." (PMID 40076766, 2025). "Several cell cycle proteins, including D- and E-type cyclins, CDKs (CDK2, CDK4, CDK6), PLK1, and Aurora kinases, are commonly overexpressed in cancers and contribute to tumor development and progression." (PMID 41154590, 2025). "They promote G0/G1 phase cell cycle arrest by upregulating p27Kip1 and p21 while downregulating cyclin D1 and cyclin‐dependent kinase 2/4 (CDK2/CDK4), thereby preventing cancer cell proliferation." (PMID 40387523, 2025). "Dual inhibition of CDK2 and CDK1 activity was explored to prevent polyploid cancer cells from reentering the cell cycle, forcing them into eliciting an apoptotic death program." (PMID 40232858, 2025). "AOH1160 repressed the expression of CDK1, CCNB1, CDK2 and CCNE2 to arrest the cell cycle at G2/M phase, thus blocking the promotion of cancer cell mitosis." (PMID 40313621, 2025). "Docking score of the identified compounds against Cyclin-Dependent Kinase 2 (PDB ID: 2A4L), Tubulin (PDB ID: 1AS0), and Epidermal Growth Factor Receptor tyrosine kinase (PDB ID: 1M17) for anti-cancer activity." (PMID 40526618, 2025). "CDK4/6 inhibitors have been proposed for use in combination therapy with a CDK2 inhibitor to prevent compensatory upregulation of CDK4/6 activity, allowing cancer cells to bypass the G1/S checkpoint." (PMID 40232858, 2025). "Many malignancies exhibit overactivation of the CDK2- CCNA2 and CDK1-CCNA2 complexes, making them a promising target for cancer therapy." (PMID 39929880, 2025). "Another, methods for decrease cancer diseases spreading are inhibition the enzymes responsible for cancer multiplicity and spreading like DHFR, CDK2, RET, TULBIN, HSP90, HSP70, EGR...etc." (PMID 39985107, 2025). "ATG10 promotes cancer growth and metastasis by modulating epithelial-mesenchymal transition and cell cycle regulators such as cyclin B1, CDK1 and CDK2." (PMID 40313244, 2025). "Molecular docking further substantiated their therapeutic relevance, showing high binding affinity to key cancer-related targets like AKT1, CDK2, ERK1, and TNFα." (PMID 40942174, 2025). "As expected, AURKA ablation significantly inhibited proliferation in all cell lines, whereas CDK2 and VPS37A knockout selectively suppressed growth in cancer cells." (PMID 40180891, 2025). "CDK2 is also regulated by upstream signals from ER and HER2 pathways, further integrating these proteins into a shared network of cancer-driving mechanisms." (PMID 39861131, 2025). "Alanazi and his team developed and evaluated a series of pyrimidine derivatives as multi-kinase inhibitors, including EGFR, VEGFR-2, CDK2, and HER2, besides the evaluation against a panel of cancer cell lines." (PMID 39404419, 2024). "Molecular docking studies indicated that both compounds fit well in the active sites of both CDK2 and CDK9, suggesting a mechanism for their action against cancer cells." (PMID 39404419, 2024).
cancer (continued). "The goal of this investigation was to design, synthesize, and evaluate a set of pyrazolo[1,5-a]pyrimidine derivatives for their dual inhibition potential toward CDK2 and TRKA kinases, along with their potential antiproliferative against cancer cell lines." (PMID 39770509, 2024). "Compounds St.14 and St.15 demonstrated significant activities against the CDK2 enzyme and exhibited strong antiproliferative activities against MCF-7 and HCT116 cancer cell lines." (PMID 39404419, 2024). "It has been observed that selective COX-2 inhibitors can affect the checkpoints in the cell cycle by reducing the levels of cyclin D1 and cyclin E. Therefore, CDK2 and COX-2 are potential targets for cancer treatment." (PMID 39404419, 2024). "Generally speaking, the protein encoded by CCNA2 can activate CDK2, which may participate in the occurrence and progression of various tumors by affecting epithelial-mesenchymal transition (EMT), metastasis, and may enhance cancer invasion, recurrence, and chemotherapy resistance." (PMID 38464517, 2024). "Their ability to suppress the growth of 60 distinct cancer cell lines was examined following the NCI protocol, and the most active compounds were subjected to CDK2 and TRKA enzyme." (PMID 39770509, 2024). "According to the preliminary pharmacophore-based screening, kaempferol, and withanolides D and O were suggested to bind with both CDK2 and BRD3, respectively, as cancer-relevant target proteins." (PMID 38303989, 2024). "Some cancer proteins such as IGF-1R kinase proteins, CDK-2, and CDK-6 bind to anthocyanidins, namely petunidin, peonidin, malvidin, pelargonidin, delphinidin, and cyanidin, thus anthocyanidins are promising metabolites for the development of cancer drugs." (PMID 39845791, 2024). "Second, in cancers where combined CDK4/6 and CDK2 inhibition is warranted, separation of these components allows for flexibility with dosing, increasing the chances of finding an effective and tolerable treatment schedule." (PMID 38047585, 2024). "The derivatives were tested for their effects on CDK2/cyclin E besides Abl kinases; additionally, their antiproliferative effects against MCF-7 and K-562 cancer lines were investigated." (PMID 39404419, 2024). "In cancer cells, for G1 to S-phase transition in the cell cycle, CDK-4 or CDK-6 make a complex with cyclin D, and CDK-2 makes a complex with cyclin-E." (PMID 36597025, 2023). "Myc has been reported to mediate stem cell-like cancer cells and EMT in TNBC, as well as Myc cooperates with Ras to induce the accumulation of active cyclins E/Cdk2 and E2F24,25,62." (PMID 36774386, 2023). "Based on importance in promoting cancer initiation as well as progression, CDK2 and CDK6 have drawn intense interest as promising therapeutic targets for cancer." (PMID 36342274, 2023). "CXCR2 activation also reduces the expression of p21 and increases the expression of cyclins and cyclin dependent kinases such as cyclin A, cyclin B1, cyclin D1, cyclin E, CDK2, and CDK6, thereby promoting the increased proliferation of cancer cells." (PMID 37686093, 2023). "CDK1 is significantly higher in 17 out of 24 or 70.8% of the cancers listed and CDK2 and CDK7 are higher in 16 out of 24 or 67% of the cancers listed." (PMID 37311884, 2023). "Molecular docking predictively simulated the interactions between these compounds and CDK2 and CCNB1 proteins involved in cancer pathways and progression." (PMID 37887429, 2023). "Given the limited information on ADORA1 in cancer pathophysiology, the observed anticancer effects can be attributed to the inhibition of the other two targets (TRIM24 and CDK2)." (PMID 37894709, 2023). "On the other hand, in cancer cells, WTAP played a role in enhancing CDK2 protein expression by binding to the 3’-UTR of the CDK2 transcript to stable the CDK2 transcript." (PMID 37297015, 2023). "The combination of CDK2 inhibitors and CDK4/6-inhibitors appears to be effective against cancer cells resistant to CDK4/6 inhibitors." (PMID 37563111, 2023).
cancer (continued). "Our studies offer insights into the conformational changes involved in cyclin-E/CDK2 and cyclin-D/CDK4 activation and their implications for drug discovery, particularly for CDK4, which is often targeted in cancer." (PMID 37790340, 2023). "Based on these results, CDK1, CDK2, CDK4, CDK5, and CDK7 are the top 5 CDKs that are highly expressed in cancer tissues compared to normal tissues." (PMID 37311884, 2023). "CDK-2 and CCNB1 are two key molecules involved in cell cycle regulation, and they have been explored as potential anti-cancer targets due to their critical roles in controlling cell division." (PMID 37887429, 2023). "According to our docking data, EM and Chr were the most attractive for cancer targeting proteins TNIK and CDK2, followed by caspase-3." (PMID 36355520, 2022). "The promising coumarin derivatives 10, 13 and 15 derivatives against Paca-2, Mel-501, PC-3 and A-375 cancer cell lines were further assessed for their inhibitory activities against EGFR, VEGFR-2 and CDK-2/cyclin A2 kinases to detect their mechanism of action." (PMID 35408446, 2022). "In these cancers, the tumor suppressive role of miR-145 is achieved, at least partially, through the regulation of cell cycle-related proteins such as CDK6, CDK2, and cyclin D1, and direct targeting of oncogenes, including N-RAS and VEGF-A." (PMID 35563814, 2022). "According to what was previously published, we found that there is a direct relationship between the inhibition of cyclin dependent kinase 2 (CDK2) and flavonoids in cancer therapy." (PMID 36676935, 2022). "Some members of CDK family including CDK1, CDK2, CDK4 and CDK6 have been reported to be involved in the regulation of cell cycle, thus participating the development and progression of cancer." (PMID 35517403, 2022). "An in silico study on three main enzymes EGFR, CDK2 and CDK4 proved the effectiveness of trans-anethole in inhibiting these enzymes and so the consequences of cancer progression." (PMID 35850583, 2022). "In comparison to the anti-cancer drug fluorouracil, Chr and EM both demonstrated better binding scores against the protein targets caspase-3, apoptosis regulator Bcl-2, TNIK, and CDK2." (PMID 36355520, 2022). "Firstly, CDK2, CDK4, and CDK6, these three CDKs are often all elevated in clinical patient samples of many cancers." (PMID 33579185, 2021). "Cyclin E1 is a cell cycle regulatory protein that activates cyclin-dependent kinase 2 (CDK2), and whose gain can promote both increased proliferation and genomic instability in cancer cells, and is frequently elevated in BLBC10." (PMID 34465787, 2021). "CDK1, CDK2, CDK4 and CDK6 subtypes are responsible for the regulation of cell-cycle progression in its different phases, moreover, they play a pivotal role in cancer cell continuous proliferation." (PMID 33327806, 2021). "For instance, tissue microarrays identified that LIN28A expression was increased in epithelial tumors and promoted cell cycle progression by regulating CDK2, CCND1, and CDC25A in cancer cells." (PMID 34868981, 2021). "Meanwhile, the inhibition of FOXM1 repressed the expression of CDK6, CCND1, CDK2, CCNE2, E2F2, and CDC25A to arrest the cell cycle at G2 phase, which blocks the promotion of cancer-cell mitosis." (PMID 34880209, 2021). "And studies have shown that SAHA generally fights against cancer by upregulating the p21 (CDKN1A) cancer suppressor gene, PTEN, p27 and decreasing levels of pro-growth genes CDK2, CDK4, cyclin D1 and cyclin E." (PMID 32682428, 2020). "The ability of hydrazino-isatin-based benzenesulfonamides in the inhibition of cyclin-dependent kinase 2 (CDK2) were previously reported, exhibiting antiproliferative activity against different cancer cell lines HT29, MDAMB468, RKO and SW620." (PMID 33614708, 2020).